PDCD1LG2 (programmed cell death 1 ligand 2)
Diseases named in the same sentence as PDCD1LG2 in open-access papers (continued):
Sharing a sentence is not in itself a finding about the gene and the disease.
colorectal cancer (33 papers, 2013 to 2025). A primary or metastatic malignant neoplasm that affects the colon or rectum. "In colorectal cancer patients, PDCD1LG2 expression is negatively correlated with Crohn’s-like lymphoid reactions, suggesting a possible link between PDCD1LG2-expressing tumor cells and adaptive antitumor immunity." (PMID 37397391, 2023). "Pdcd1lg2 mainly located or bound to monocyte/macrophage in colorectal cancer." (PMID 37006239, 2023). "Furthermore, the relationship between SIGLEC15,TIGIT,LAG3,CTLA4, PDCD1LG2 immune checkpoints and Mapk14 was only verified by correlation analysis, and we need to further explore the mechanism of Mapk14 expression in colorectal cancer in vitro and vivo experiments, such as single cell RNA sequencing." (PMID 35141222, 2022). "The results showed that in colorectal cancer, the high expression of NOLC1 was closely related to multiple immune checkpoints, such as LAG3, CTLA-4, and PDCD1LG2, leading to immune tolerance or escape of tumor cells." (PMID 37670166, 2023).
ovarian carcinoma (32 papers, 2013 to 2025). A malignant neoplasm originating from the surface ovarian epithelium. "In support of an antitumor tumor immune response, by targeting intracellular PD-L1 with a cell-penetrating antibody, the mRNA expression of PDCD1LG2, BIRC3, RELB, and VSIR was significantly decreased in ovarian cancer cells." (PMID 39996786, 2025). "We also found a significant positive correlation between PD-L1 (CD274) and the PDCD1LG2, BIRC3, RELB, and VSIR genes in the TCGA ovarian cancer-patient database." (PMID 39996786, 2025).
esophageal cancer (31 papers, 2012 to 2025). A primary or metastatic malignant neoplasm involving the esophagus. "Typically, the abnormal expression level of CD274 and PDCD1LG2 was detected in both esophageal carcinoma (ESCA) and stomach adenocarcinoma (STAD), where PDCD1LG2 was related to the overall survival (OS) of the patients in ESCA (p = 0.015) and STAD (p = 0.025)." (PMID 33833994, 2021).
non-small cell lung carcinoma (31 papers, 2015 to 2025). A group of at least three distinct histological types of lung cancer, including non-small cell squamous cell carcinoma, adenocarcinoma, and large cell carcinoma. "The underlying reason of the increased expression of CD274 and PDCD1LG2 in ATC with CDKN2A loss is not unveiled in this study, but their potential relationship in non-small cell lung cancer were previously reported." (PMID 31235699, 2019).
Hodgkins lymphoma (29 papers, 2015 to 2025). A heterogeneous group of malignant lymphoid neoplasms of B-cell origin characterized histologically by the presence of Hodgkin and Reed-Sternberg (HRS) cells in the vast majority of cases. "Genes in NK cells (i.e., BCL11B for T-ALL, MAP3K7IP2 for prostate cancer) and in monocytes (i.e., LCK and BCL11B for T-ALL, PDCD1LG2 for Hodgkin’s lymphoma, PRDM16 for AML, CACNA1D for prostate cancer) were found significant in our meta-EWAS." (PMID 38466776, 2024). "In B cells, PRDM16 and DNMT3A for AML, PDCD1LG2 for Hodgkin’s lymphoma, LMNA for spritzed tumor, and BCL11B for T-cell acute lymphoblastic leukemia (T-ALL) harbored DMPs for HIV infection." (PMID 38466776, 2024). "Furthermore, in Hodgkin lymphoma, chromosomal abnormalities of 9p24.1,a genomic region that includes CD274, PDCD1LG2 (encoding PD-L), and Janus kinase 2(JAK2), have been correlated with increased PD-L1 expression." (PMID 26361042, 2015). "Recently in classic Hodgkin lymphoma, a 9p24.1 amplification involving CD274 (PD-L1) and PDCD1LG2 (PD-L2) was shown to predict response to nivolumab outcomes." (PMID 34234122, 2021).
lung adenocarcinoma (28 papers, 2017 to 2025). A carcinoma that arises from the lung and is characterized by the presence of malignant glandular epithelial cells. "We were intrigued to see that the PD-1 ligands PD-L1(CD274 gene) and PD-L2 (PDCD1LG2 gene) mRNA were among top significant genes that were positively correlated with IDO1 mRNA in lung adenocarcinoma tumors." (PMID 37985999, 2023). "Finally, we found that the immune checkpoint genes CD274(PD-L1) and PDCD1LG2(PD-1) were also related to SPP1 in lung adenocarcinoma." (PMID 36688087, 2023). "Finally, we found that the immune checkpoint-related genes CD274(PD-L1) and PDCD1LG2(PD-1) was related to SPP1 in lung adenocarcinoma." (PMID 36688087, 2023). "Considering our discoveries that IL-1β prompts the upregulation of CD274 and PDCD1LG2 mRNA, as well as PD-L1 protein in lung adenocarcinoma cell lines, it is conceivable that heightened tumor or circulating IL-1β might additionally enhance the PD-1/PD-L1 axis’s suppression of cytotoxic T-cells." (PMID 37985999, 2023). "Interestingly, PD-L2 gene (PDCD1LG2) single nucleotide polymorphisms (SNPs) are associated with lung adenocarcinoma risk in female never-smokers, and 3 of these SNPs were negatively associated with PD-L2 expression in non-tumor tissue, but not in tumor tissue." (PMID 36091058, 2022). "Analysis of lung adenocarcinoma patient data set from TCGA revealed that IDO1 expression was positively correlated with CD274 and PDCD1LG2 expression." (PMID 37985999, 2023).
hepatocellular carcinoma (27 papers, 2012 to 2025). A malignant tumor that arises from hepatocytes. "In addition, PDCD1LG2 overexpression is associated with poor prognosis in hepatocellular carcinoma patients." (PMID 35198632, 2022).
Autoimmunity (25 papers, 2016 to 2025). The occurrence of an immune reaction against the organism's own cells or tissues. "CD274 (also known as B7-H1) and its paralog, PDCD1LG2 (programmed cell death 1 ligand 2, also known as B7-DC), are types of transmembrane protein normally expressed on immunocytes, which function in preventing autoimmunity under infected conditions." (PMID 28286742, 2017).
colon carcinoma (22 papers, 2020 to 2025). "Some checkpoint-related genes (BTLA, CD80, CD86, CTLA4, IDO1, PDCD1LG2, and TIGIT) had decreased expression in the KRAS-mutated group, providing potential opportunities for immunotherapy in colon cancer." (PMID 33254149, 2020). "Seven checkpoint-related genes (BTLA,CD80, CD86, CTLA4, IDO1, PDCD1LG2, and TIGIT) had decreased expression in the KRAS-mutated group, providing potential opportunities for immunotherapy in colon cancer." (PMID 33254149, 2020). "PDCD1LG2 (programmed cell death 1 ligand 2, also called PDCD1 ligand 2, PD-L2, or CD273) is an independent prognostic factor and is associated with the intratumoral infiltration of CD8 + TILs in colon cancer." (PMID 38904744, 2024). "Analysis of colon cancer cohort in TCGA database showed that APC mutation was associated with a lower TMB and was associated with a lower genes expression of PDCD1 (PD-1), CD274 (PD-L1) and PDCD1LG2 (PD-L2)." (PMID 36977982, 2023). "The results showed that PDCD1LG2, ICOS, CD86, CD80, CD48, and CD274 showed a significant exclusion situation from RFX1 expression in colon cancer." (PMID 41425715, 2025).
osteosarcoma (21 papers, 2018 to 2025). A usually aggressive malignant bone-forming mesenchymal neoplasm, predominantly affecting adolescents and young adults. "Beside these, we do not see any significant correlation between expression levels of CD274 and PDCD1LG2 genes, that encodes PD-L1 and PD-L2 respectively, with the expression levels of PDCD1 and IFNG, and the percentage of CD8 T cells in osteosarcoma tumors." (PMID 33757216, 2021). "Relatively low expression levels of CTLA4, HAVCR2, LAG3, and PDCD1LG2 can be observed in the group of patients with metastasis (p < 0.05), which may indicate and predict a poor prognosis in patients with osteosarcoma." (PMID 38256356, 2024). "Besides, PDCD1LG2 blockade may become potential immunotherapeutic intervention targets enhancing the cytotoxic effects against osteosarcoma." (PMID 39569192, 2024). "Previous studies have also found that CD44, CD40, PDCD1LG2, LAG3, and HAVCR2 can be immunotherapeutic targets for osteosarcoma." (PMID 38071320, 2023). "This study found that macrophage M1 was positively correlated with immune checkpoints PDCD1, CD274 (PD-L1), PDCD1LG2, CTLA4, and TIGIT, suggesting the opportunity of ICBs therapy in osteosarcoma patients with high infiltrating macrophage M1." (PMID 34335756, 2021).
glioblastoma (19 papers, 2018 to 2025). The most malignant astrocytic tumor (WHO grade IV). "Furthermore, HSChigh glioblastoma samples associated with the expression of immune checkpoint molecules, including PD-1 (PDCD1, p = 2.7 × 10−4), PD-L1 (CD274, p = 0.016), and PD-L2 (PDCD1LG2, p = 0.003)." (PMID 34162860, 2021). "We conducted expression profiling of CD274 (PD-L1), GATA3, IFNG, IL12R, IL12RB2, IL4, PDCD1 (PD-1), PDCD1LG2 (PD-L2), and TBX21 (T-bet) using data of 158 glioblastoma multiforme (GBM) patients with clinical information available at The Cancer Genome Atlas." (PMID 29721184, 2018).
Sepsis (18 papers, 2011 to 2025). Sepsis is defined as life-threatening organ dysfunction caused by a dysregulated host response to infection. "In the high-risk group, LAIR1 was also elevated, as were immunosuppressive genes CD276, ICOSLG, and PDCD1LG2, which is consistent with immunosuppressive status in sepsis patients and further indicates that poor prognosis in patients with sepsis may be closely linked to immunosuppression." (PMID 40504881, 2025). "Meanwhile, CD274, PDCD1LG2, and SLGLEC15 were upregulated in sepsis, but these changes were not statistically significant." (PMID 40070882, 2025).
bladder cancer (15 papers, 2015 to 2024). "Through CRISPR/Cas9 knockout (KO) and constitutive activation (CA) strategies on SPHK1 in the bladder cancer cells, we demonstrated the potential downstream target could be programmed cell death 1 ligand 2 (PD-L2)." (PMID 39284838, 2024).
metastatic melanoma (12 papers, 2018 to 2024). A melanoma that has spread from its primary site to another anatomic site. "In summary, this study reports the promising association of individual immunotherapy panel markers CD274, PDCD1LG2, CD8A, IRF1 and a combined L1/L2 score (CD274 & PDCD1LG2) with improved immunotherapy outcome in metastatic melanoma." (PMID 31533832, 2019).
cervical cancer (11 papers, 2017 to 2025). A primary or metastatic malignant neoplasm involving the cervix. "In cervical cancer, TGCA amplifications in CD274 (PD-L1) and PDCD1LG2 (PD-L2) immune targets were found to be associated with this type of cancer, and PD-L1 amplification and polysomy have been shown to represent valid prognostic biomarkers in the treatment with anti-PD-L1s." (PMID 37341812, 2024). "CD274 and PDCD1LG2 are immunotherapy targets with amplifications reported in cervical cancer." (PMID 28771191, 2017). "Among those, ERBB2, CD274 (PD-L1), and PDCD1LG2 (PD-L2) had amplifications that highlight the potential for clinical trials of ERBB2 inhibitors and immunotherapeutic strategies for a subset of cervical cancers." (PMID 34680987, 2021). "DNA status analysis by FISH showed that most of the evaluable cervical cancer cases had disomy of chromosome 9 with two signals for both the CD274 (PD-L1) and PDCD1LG2 (PD-L2) locus (n = 43, 81%)." (PMID 33424844, 2020).
endometrial cancer (11 papers, 2014 to 2025). Primary or metastatic malignant neoplasm involving the endometrium (mucous membrane that lines the endometrial cavity). "First, we included the expression profile data of all normal endometrial samples and endometrial cancer samples of TCGA and observed the expression levels of common immune checkpoints, including PDCD1, CD274 (PDL1), PDCD1LG2 (PDL2), CTLA4, LAG3, and HAVCR2." (PMID 37872211, 2023).
liver cancer (11 papers, 2020 to 2024). An epithelial or non-epithelial malignant neoplasm that arises from the liver. "The mRNA expression levels of immune checkpoint-related genes were significantly higher in the high-risk group than in the low-risk group, especially for immune checkpoint-related genes commonly used in liver cancer immunotherapy, including (PD-L1, PDCD1LG2, PDCD1, TIGIT, TIM-3, CTLA4)." (PMID 36814910, 2023).
lupus (9 papers, 2014 to 2025). "In systemic lupus erythematosus (SLE), lysosomal‐associated membrane protein 3, the CD83 molecule (CD83) and programmed cell death 1 ligand 2 may be downstream targets of METTL1 and are involved in abnormal immunological responses." (PMID 39979979, 2025).
COVID-19 (8 papers, 2020 to 2025). A disease caused by infection with severe acute respiratory syndrome coronavirus 2. "Interestingly, macrophages from severe COVID-19 patients expressed higher levels of CD274 (PD-L1) yet the expression of PDCD1LG2 (PD-L2) was not significantly different between moderate and severe patients." (PMID 33178221, 2020).
lymph node metastasis (7 papers, 2018 to 2024). "CD274 and PDCD1LG2 not only impacted the prognosis of patients with cancer but were associated with clinical characteristics (lymph node metastasis, tumor stage, and sex) in kidney renal papillary cell carcinoma, thyroid carcinoma, and some other cancer types." (PMID 36276934, 2022). "Furthermore, high expression levels of CD274 and PDCD1LG2 were restrictively associated with lymph node metastasis in THCA and found to be associated with tumor stage in BLCA." (PMID 36276934, 2022).
brain tumors (6 papers, 2018 to 2025). "We hypothesized that AQP4 could also be the regulatory factors of various immune checkpoints in brain tumors, such as TIM-3 (HAVCR2), PD-L1 (CD274), PD-L2 (PDCD1LG2), and CEACAM1." (PMID 34113257, 2021).
mesothelioma (4 papers, 2021 to 2025). A usually malignant and aggressive neoplasm of the mesothelium which is often associated with exposure to asbestos. "IRF3 expression and the immune checkpoint genes significantly correlated with LAG3 and LGALS1 (Galectin) genes expression in mesothelioma cells, while positive correlation was found between IRF3 and HAVCR2 (TIM-3) or PDCD1LG2 (PD-L2) expression in monocytes/macrophages." (PMID 34768716, 2021).
oral cancer (4 papers, 2017 to 2025). "In particular, the regulation of CD274 and PDCD1LG2 in oral cancer cells induced by P. gingivalis was recently reviewed as a part of important mechanisms involved in the association between oral bacteria and cancer, which was consistent with our findings." (PMID 28286742, 2017).
Arthritis (3 papers, 2013 to 2023). Inflammation of a joint. "Recently, PDCD1LG2 has been associated with bone loss in arthritis, in both mouse models and patients." (PMID 37388246, 2023).
cervical squamous cell carcinoma (3 papers, 2019 to 2025). A squamous cell carcinoma arising from the cervical epithelium. "It has been shown that up to 70% of cervical squamous cell carcinoma (SCC) tissues have amplification of CD274 and PDCD1LG2 that encode PD‐L1 and PD‐L2, respectively." (PMID 40908776, 2025).
endometriosis (3 papers, 2022 to 2025). The growth of functional endometrial tissue in anatomic sites outside the uterine body. "We found that PDCD1 was significantly higher in the endometrium, while PDCD1LG2 was substantially higher in endometriosis." (PMID 40165344, 2025). "In addition, we explored the immune checkpoints (PDCD1, PDCD1LG2, CTLA4, TNFRSF9, and TNFRSF4) expression levels between the endometrium and endometriosis." (PMID 40165344, 2025).
lung disease (3 papers, 2019 to 2025). "A recent study demonstrated that nine genes (CD274, CEACAM1, CR1, FCGR1A/B, IFITM1, IRAK3, LILRA6, MAPK14, and PDCD1LG2) showed 100% sensitivity and specificity that distinguished patients with active TB from those with other lung diseases (OPD)." (PMID 38674369, 2024).
pulmonary TB (3 papers, 2015 to 2021). "Correlation between PDCD1LG2 SNPs and pulmonary TB for lung adenocarcinoma susceptibility." (PMID 34631591, 2021).
rectum adenocarcinoma (3 papers, 2019 to 2023). An adenocarcinoma arising from the rectum. "In rectal adenocarcinoma, chromothripsis on chromosome 9 results in the deletion and low expression of CD274 and PDCD1LG2 genes, which may play important roles in the poor response to immunotherapy." (PMID 36761982, 2023).
sarcoidosis (3 papers, 2016 to 2023). Sarcoidosis is a multisystemic disorder of unknown cause characterized by the formation of immune granulomas in involved organs. "Another interesting protein with differential expression higher in the BALF in sarcoidosis compared to controls, programmed cell death 1 ligand 2 (PD-L2), is a ligand for programmed death-1 (PD1) receptor." (PMID 32764642, 2020).
autoimmune thyroiditis (2 papers, 2023 to 2025). "Furthermore, it has been revealed that differential methylation status HLA -DPB1 and PDCD1LG2 genes played a role in developing autoimmune thyroiditis." (PMID 37059863, 2023).
allergic rhinitis (1 paper, 2025). Inflammation of the nasal mucous membranes caused by an IgE-mediated response to external allergens. "Polymorphic variants of PDCD1LG2 are associated with allergic rhinitis." (PMID 41516283, 2025).
medulloblastoma (1 paper, 2013). A malignant, invasive embryonal neoplasm arising from the cerebellum. "In addition, the method identified the PDCD1LG2/CD274 region, 17p13.3, a region that has been implicated as a tumor-suppressor region in medulloblastoma, where it is deleted in 40% of cases and ARID1B, a member of the SWI/SNF chromatin remodeler complex implicated in differentiation and development." (PMID 23531283, 2013).
uveal melanoma (1 paper, 2025). A melanoma derived from melanocytes of the uveal tract. "Similarly, in uveal melanoma (UVM) and liver hepatocellular carcinoma (LIHC), CRABP2 expression is significantly correlated with seven of these immune checkpoint genes (LAG3, CTLA4, PDCD1LG2, HAVCR2, PDCD1, CD274, and TIGIT)." (PMID 39991584, 2025).